PCDHGA9 (protocadherin gamma subfamily A, 9)
Description:
Potential calcium-dependent cell-adhesion protein. May be involved in the establishment and maintenance of specific neuronal connections in the brain.
Synonyms: PCDH-gamma-A9
Tractability: Antibody: UniProt places it where antibodies can reach, with medium confidence; UniProt predicts a signal peptide or a membrane-spanning region; its Gene Ontology location is reachable by antibodies, with medium confidence. PROTAC: its protein half-life has been measured.
Gene: Protein-coding gene on chromosome 5 (141,402,778 to 141,512,975, forward strand). Ensembl gene ENSG00000261934.
Subcellular location: Cell membrane
Subcellular location (Human Protein Atlas): Plasma membrane; Vesicles; Cytosol; Nucleoplasm
Gene Ontology:
Molecular function: protein binding; RNA binding; cell adhesion molecule binding; calcium ion binding
Biological process: cell adhesion; homophilic cell-cell adhesion
Cellular component: plasma membrane; membrane
Genetic constraint (gnomAD): Loss-of-function variants: 37 observed, 66.07 expected, observed/expected ratio (o/e) 0.56, 90% interval 0.43 to 0.74. The upper end of that interval is the gene's LOEUF score, 0.74, which puts it in group 3 of 6, group 1 being the genes least tolerant of losing a copy. Missense variants: 1,138 observed, 1,234.6 expected, observed/expected ratio (o/e) 0.92, 90% interval 0.88 to 0.97. Synonymous variants: 459 observed, 515.7 expected, observed/expected ratio (o/e) 0.89, 90% interval 0.82 to 0.96.
Homologues: Orthologues: mouse Pcdhga9 (84% identical). Paralogues in human: PCDHGA8 (80% identical), PCDHGA10 (79% identical), PCDHGA7 (74% identical), PCDHGA4 (74% identical), PCDHGA12 (73% identical), PCDHGA6 (73% identical), PCDHGA5 (73% identical), PCDHGA3 (73% identical), PCDHGA11 (72% identical), PCDHGA1 (72% identical), PCDHGA2 (72% identical), PCDHGB5 (51% identical), and 49 more.
Diseases named in the same sentence as PCDHGA9 in open-access papers:
PCDHGA9 is named in the same sentence as 10 diseases in open-access papers, as found by Europe PMC text mining. Sharing a sentence is not in itself a finding about the gene and the disease. The quoted sentences say what the papers report.
gastric cancer (5 papers, 2018 to 2024). A primary or metastatic malignant neoplasm involving the stomach. "For example, knockdown of PCDHGA9 promoted migration and invasion of gastric cancer cells, while PCDHGA9 overexpression inhibited proliferation and metastasis of gastric cancer cells." (PMID 39208202, 2024). "In our previous study, we found that PCDHGA9 expression was reduced in gastric cancer tissues compared with corresponding paraneoplastic tissues." (PMID 39587482, 2024). "Our previous investigation in gastric cancer revealed the inhibitory role of PCDHGA9 in the Wnt/β-catenin pathway, and here we extended similar research in colorectal cancer." (PMID 39587482, 2024). "Thus, we conducted Transwell and wound healing assays, which showed that, contrary to findings in our previous gastric cancer research, the overexpression of PCDHGA9 in CRC cells resulted in decreased expression of β-catenin." (PMID 39587482, 2024). "Furthermore, in gastric cancer, PCDHGA9 was shown to reduce SMAD2/3 nuclear translocation suppressing Snail expression, resulting in changes in cell–cell adhesion proteins, including E-cadherin." (PMID 37748077, 2023). "Moreover, overexpression or depletion of PCDHGA9 induced a decrease or increase, respectively, in the migration and invasion of gastric cancer cells, and PCDHB3 inhibited the migration of CRC cells." (PMID 37748077, 2023). "In this study, we investigated the impact of PCDHGA9 on the invasion and metastasis abilities of CRC on the basis of our previously identified functional characteristics in gastric cancer." (PMID 39587482, 2024). "Regarding the differential effect of PCDHGA9 on the Wnt/β-catenin pathway between CRC and gastric cancers, varying HOXA1 and CXCR4 expression levels in these cancers might explain this difference." (PMID 39587482, 2024).
acute lymphoblastic leukemia (1 paper, 2018). Leukemia with an acute onset, characterized by the presence of lymphoblasts in the bone marrow and the peripheral blood. "Recently, the aberrant expression of PCDHGA9 has been reported in some cancers with unfavorable prognosis, such as acute lymphoblastic leukemia, nasopharyngeal carcinoma, and astrocytoma." (PMID 29348665, 2018).
colorectal cancer (1 paper, 2024). A primary or metastatic malignant neoplasm that affects the colon or rectum. "PCDHGA9 expression was detected using quantitative real-time quantitative polymerase chain reaction (RT-qPCR) in 63 pairs of colorectal cancer tissues." (PMID 39587482, 2024). "To assess the expression of PCDHGA9 in colorectal cancer tissues, we selected 63 paired tissue specimens from colorectal cancer patients who had undergone radical surgery at Shanghai General Hospital between 2013 and 2014, which were then subjected to RNA extraction and subsequent qRT-PCR analysis." (PMID 39587482, 2024). "Moreover, we used clinical specimens to establish a combined molecular prognostic model involving miR-1269a and PCDHGA9 and evaluated the expression of miR-1269a in 63 colorectal cancer patient tissues." (PMID 39587482, 2024). "However, in CRC, we found that PCDHGA9 affected β-catenin in another way to inhibit the Wnt pathway, EMT in colorectal cancer cells, and CRC invasion and metastasis." (PMID 39587482, 2024).
lung carcinoma (1 paper, 2024). "These genes include GRIA3, TAF7L, ARL14, PCDHGA9, MDGA1, ZFPM2, OSR2, TMC8/TMC6, HCN2, and CDK5R2, which are likely to be relevant in human lung cancer and are also epigenetically deregulated upon exposure to ECS in our animal study." (PMID 39273313, 2024).
lymph node metastasis (1 paper, 2020). "PCDHGA9 expression in GC tissues was negatively correlated with differentiation, tumour size, lymph node metastasis, UICC stage and methylation level." (PMID 32231199, 2020).
metastasis (1 paper, 2020). The spread or migration of cancer cells from one part of the body (where they first appeared) to another. "The IHC results from the clinical samples revealed that PCDHGA9 expression was lower in GC tissues than in matched normal mucosa samples, and patients with liver metastasis showed significantly lower PCDHGA9 expression than did patients without metastasis." (PMID 32231199, 2020).
tumor (3 papers, 2018 to 2024). "Low PCDHGA9 expression was frequently correlated with low E-cadherin expression and high N-cadherin, Vimentin and Twist expression in tumour tissues." (PMID 32231199, 2020). "Cells with lower PCDHGA9 expression had significantly larger tumour sizes and faster xenograft formation than did the respective control cells." (PMID 32231199, 2020). "In general, PCDHGA9 acts as a tumour suppressor, and low PCDHGA9 expression indicates an aggressive type in GC." (PMID 32231199, 2020). "PCDHGA9 was mainly expressed in normal mucosa, and the staining was significantly stronger than that in tumor tissue." (PMID 29348665, 2018). "PCDHGA9 knockdown promoted GC cell proliferation, migration, and invasion, whereas PCDHGA9 overexpression inhibited GC tumor growth and metastasis but induced apoptosis, autophagy, and G1 cell cycle arrest." (PMID 29348665, 2018). "PCDHGA9, acting as a tumor suppressor, is downregulated by miR-1269a." (PMID 39587482, 2024). "PCDHGA9 acts as a tumor suppressor with anti-invasive and metastatic ability in CRC." (PMID 39587482, 2024). "Together, these data indicate that PCDHGA9 acts as a tumor suppressor with anti-proliferative activity and anti-invasive ability, and the reduction of PCDHGA9 could serve as an independent prognostic biomarker in GC." (PMID 29348665, 2018). "Next, we determined whether tumor cell growth inhibition by PCDHGA9 was related to cell cycle arrest." (PMID 29348665, 2018). "Furthermore, organs metastases were observed in the control group, revealing that overexpression of PCDHGA9 inhibited tumor colonization, migration and invasion." (PMID 29348665, 2018). "The effects of PCDHGA9 on GC tumor growth and metastasis were examined both in vivo and in vitro." (PMID 29348665, 2018). "The present study showed that PCDHGA9 was downregulated in human GC cell lines and tumor tissues and that PCDHGA9 overexpression could inhibit GC cell proliferation, migration, and invasion both in vivo and in vitro." (PMID 29348665, 2018). "Although the precise mechanism for PCDHGA9-regulated autophagy in GC cells remains unknown, these results suggest that PCDHGA9 restrains tumor proliferation through the induction of autophagy in GC cells." (PMID 29348665, 2018). "Enhanced expression of PCDHGA9 generated smaller tumor volumes in subcutaneous xenografts." (PMID 29348665, 2018). "Therefore, the aim of the present study was to examine whether PCDHGA9 suppresses tumor cell proliferation via interaction with β-catenin that disrupt canonical Wnt signaling in GC." (PMID 29348665, 2018). "In this study, we examined the expression of PCDHGA9 in CRC tissues and found that PCDHGA9 expression was reduced in CRC compared with paraneoplastic tissues and correlated with tumor differentiation, staging, and invasion." (PMID 39587482, 2024). "We randomly selected 12 matched pairs of clinical tumours and their corresponding normal mucosae, and BSP demonstrated that PCDHGA9 was methylated in tumour tissues with reduced PCDHGA9 expression but not in normal mucosa samples." (PMID 32231199, 2020). "The reduction of PCDHGA9 expression in GC was remarkably correlated with the T stage (p < 0.001), N stage (p = 0.003), M stage (p = 0.006), UICC stage (p < 0.001), histological differentiation (p = 0.001), and tumor relapse (p = 0.001)." (PMID 29348665, 2018).
PCDHGA9 also shares sentences with these, for which no sentence is quoted: cancer (2 papers); colorectal tumors (1); nasopharyngeal carcinoma (1).